MED26 (mediator complex subunit 26)
Description:
Component of the Mediator complex, a coactivator involved in the regulated transcription of nearly all RNA polymerase II-dependent genes. Mediator functions as a bridge to convey information from gene-specific regulatory proteins to the basal RNA polymerase II transcription machinery. Mediator is recruited to promoters by direct interactions with regulatory proteins and serves as a scaffold for the assembly of a functional pre-initiation complex with RNA polymerase II and the general transcription factors.
Synonyms: CRSP7; CRSP70
Tractability: Small molecule: a structure with a bound ligand is known. PROTAC: ubiquitination databases record sites on it.
Gene: Protein-coding gene on chromosome 19 (16,574,907 to 16,629,062, reverse strand). Ensembl gene ENSG00000105085.
Subcellular location: Nucleus
Subcellular location (Human Protein Atlas): Nucleoplasm; Mitotic chromosome
Pathways (Reactome):
Developmental Biology: Transcriptional regulation of white adipocyte differentiation
Disease: RSV-host interactions
Gene expression (Transcription): Generic Transcription Pathway
Metabolism: PPARA activates gene expression
Gene Ontology:
Molecular function: protein binding; transcription coregulator activity; transcription coactivator activity
Biological process: regulation of transcription by RNA polymerase II; positive regulation of gene expression; positive regulation of transcription elongation by RNA polymerase II; positive regulation of transcription initiation by RNA polymerase II; RNA polymerase II preinitiation complex assembly; transcription initiation at RNA polymerase II promoter
Cellular component: core mediator complex; mediator complex; nucleus; nucleoplasm
Genetic constraint (gnomAD): Loss-of-function variants: 7 observed, 40.32 expected, observed/expected ratio (o/e) 0.17, 90% interval 0.098 to 0.33. The upper end of that interval is the gene's LOEUF score, 0.33, which puts it in group 1 of 6, group 1 being the genes least tolerant of losing a copy. Missense variants: 784 observed, 834.39 expected, observed/expected ratio (o/e) 0.94, 90% interval 0.88 to 1. Synonymous variants: 375 observed, 365.31 expected, observed/expected ratio (o/e) 1.03, 90% interval 0.94 to 1.12.
Homologues: Orthologues: chimpanzee MED26 (99% identical), macaque MED26 (95% identical), pig MED26 (93% identical), dog MED26 (90% identical), rat Med26 (86% identical), mouse Med26 (85% identical), guinea pig MED26 (82% identical), tropical clawed frog med26 (60% identical), Drosophila melanogaster MED26 (25% identical).
Diseases named in the same sentence as MED26 in open-access papers:
MED26 is named in the same sentence as 4 diseases in open-access papers, as found by Europe PMC text mining. Sharing a sentence is not in itself a finding about the gene and the disease. The quoted sentences say what the papers report.
cancer (2 papers, 2022 to 2023). A tumor composed of atypical neoplastic, often pleomorphic cells that invade other tissues. "MED26, belonging to the Mediator complex (MED) gene family, while implicated in several cancer types, does not include PCa." (PMID 37444571, 2023).
infection (1 paper, 2015). The state of being infected such as from the introduction of a foreign agent such as serum, vaccine, antigenic substance or organism. "This form of mediator possesses the kinase domain, but lacks med26, and thus may be involved in repression, possibly of immediate early promoters late after infection." (PMID 26018390, 2015).
MED26 also shares sentences with these, for which no sentence is quoted: Infertility (1 paper); tumour (1).